EGR1 (early growth response 1)
Diseases named in the same sentence as EGR1 in open-access papers (continued):
Sharing a sentence is not in itself a finding about the gene and the disease.
cardiac hypertrophy (continued). "Early growth response-1 (EGR1) plays a role in the pathogenesis of atherosclerotic lesions, intimal thickening after acute vascular injury, ischemic pathology, angiogenesis, allograft rejection, and cardiac hypertrophy." (PMID 23185530, 2012). "Increasing evidence has demonstrated that Ang II, via its type 1 receptor, activates a number of signaling pathways, including ROS, and transcriptional factors such as NF-κB, Ets-1, and early growth response 1 to regulate cardiac hypertrophy, inflammation, and fibrosis." (PMID 22558139, 2012). "Furthermore, our findings suggest that HDAC5 may regulate MEF2A expression through the ERK/EGR1 signaling pathway, contributing to the progression of myocardial hypertrophy." (PMID 37667300, 2023). "Thus, F2 could protects cardiomyocytes from I/R or H/R injury via inhibition of the Egr-1/ROS positive feedback loop, which might extend its use in oxidative stress-related diseases such as cardiac hypertrophy." (PMID 29422863, 2018). "This may be reflected by the reduced cardiac hypertrophy in the Egr1 knockout mice." (PMID 28790436, 2017). "In this regard, recent studies indicate that the naturally occurring agent astragaloside IV inhibits cardiac hypertrophy through ERK and PKCβII/Egr-1 activation in rodents born from mothers with intrauterine hypoxia." (PMID 39619154, 2024). "A total of six hub genes (TANC2, ADAMTS2, DYNLL1, MRC2, EGR1, and OTUD1) were considered cardiac hypertrophy and HF regulators." (PMID 37498303, 2023). "Six hub genes (TANC2, ADAMTS2, DYNLL1, MRC2, EGR1, and OTUD1) showed anomaly trend in cardiac hypertrophy." (PMID 37498303, 2023). "As Egr1 and Egr3, two paralogous genes of Egr2, are both CV genes, and Egr2 is likely a CV gene and an essential regulator for TAB-induced cardiac hypertrophy." (PMID 28790436, 2017). "Acetate also downregulates Egr1, a master transcriptional regulator of cardiac and renal inflammation, and signals via GPR43/109a to reduce RAAS activation and cardiac Nppb expression, a marker of cardiac hypertrophy and heart failure." (PMID 40806090, 2025). "However, the relationship between HDAC5, ERK/EGR1 signaling, and MEF2A in the context of cardiac hypertrophy remains unclear." (PMID 37667300, 2023). "Our finding suggests that Egr1 participates in developing stage of cardiac hypertrophy but may not be required for the compensatory stage of hypertrophy." (PMID 28790436, 2017).
glioblastoma (30 papers, 2012 to 2025). The most malignant astrocytic tumor (WHO grade IV). "The transcriptomic analysis also revealed that GZ17-6.02 treatment results in suppression of several genes implicated in glioblastoma growth and invasion, such as EGR1, ASCL1, CD109, ABCG2, and CDH5." (PMID 35456993, 2022). "PDGF ligands stimulated early growth response 1 (EGR1) transcription to induce METTL3 to promote glioblastoma stem cells (GSC) proliferation and self-renewal." (PMID 36835633, 2023). "In glioblastoma specifically, EGR1 is shown to promote the invasion and proliferation of malignant cells, and higher levels of this transcription factor serve as an unfavorable prognostic marker." (PMID 35456993, 2022). "It was demonstrated that EGR1 positively regulates the activity of the FN gene, and that cell adhesion and migration were greatly increased in the EGR1-expressing glioblastoma cells." (PMID 28279210, 2017). "The NOX2/Egr-1/Fyn pathway was also conserved within TKI-resistant EGFRΔIII-expressing glioblastoma and patient-derived glioblastoma stem cells." (PMID 26136341, 2015). "For example, early growth response gene-1 (EGR-1) regulates TF expression under hypoxic conditions in glioblastoma multiforme." (PMID 24086497, 2013). "Overexpression of EGR1 promotes tumor growth in kidney cells but suppresses growth and transformation in other cell types, e.g. fibroblasts and glioblastoma cells." (PMID 23072359, 2012). "A recent study revealed that the induction of EGR1 could trigger glioblastoma cell dedifferentiation into a stem-like state, which involved the expression of pluripotent markers NANOG and OCT4." (PMID 34051854, 2021). "NOX2 has been suggested as a potential target in the development of a therapy against chronic myeloid leukemia (CML) and glioblastoma, as the resistance of CML stem cells and patient-derived glioblastoma stem cells to tyrosine kinase inhibitors seem to be mediated through the NOX2/Egr1/Fyn axis." (PMID 28626501, 2017). "Zhx1 promoted the proliferation, migration, and invasion of glioblastoma cells and cholangiocarcinoma cells by activating the transcription of the EMT genes Snail2 and Twist1 or enhancing the Egr1 expression, respectively." (PMID 37452012, 2023). "Similarly, in a glioblastoma (GBM) stem cells (GSCs) related work, platelet-derived growth factor (PDGF) ligand stimulate early growth response 1 (EGR1) transcription to induce METTL3 to promote GSC proliferation and self-renewal." (PMID 38562618, 2024).
Obesity (30 papers, 2015 to 2026). Accumulation of substantial excess body fat. "Among these factors, the association between Egr1 and obesity has been documented in other systems, suggesting a certain level of complexity." (PMID 40141675, 2025). "Egr1-deficient mice fed an HFD are less susceptible to diet-induced obesity and obesity-associated disorders such as insulin resistance, hyperinsulinemia, hyperlipidemia, and fatty liver." (PMID 38619434, 2024). "Egr1 is thus a good therapeutic target to counteract obesity and associated fibrosis since its loss-of-function reduces ECM production and stimulates the white fat browning process." (PMID 32121305, 2020). "In contrast, Egr1 knock-out mice display an increased energy expenditure and are protected from high fat diet-induced obesity and obesity-associated pathologies." (PMID 32985557, 2020). "The zinc finger transcription factor early growth response-1 (EGR1) is expressed in adult adipose tissues, where its overexpression has been linked to obesity in both humans and mouse models." (PMID 33383883, 2020). "Egr1 is expressed in adult adipose tissues where its overexpression has been linked to obesity and obesity-associated metabolic disorders in both humans and mouse models." (PMID 29170465, 2017). "An increase of EGR1 in adipose tissue is associated with insulin resistance and obesity." (PMID 33952720, 2021). "Increased Egr1 expression has been linked to obesity in both humans and murine models." (PMID 32985557, 2020). "To understand how Egr1 can both be linked with obesity and adverse metabolic outcomes while repressing differentiation of white adipocytes in culture, we investigated the role of Egr1 in white adipose tissue development during the postnatal period in female mice." (PMID 29170465, 2017). "The link of Egr1 to obesity and obesity-associated fatty liver has been reported in mouse studies." (PMID 29607419, 2017). "Linagliptin, another DPP4 inhibitor, was suggested to have a cardioprotective role through FGF-2/EGR-1 pathway in mice with dietary obesity, and capillary rarefaction was suggested to be important in this process." (PMID 41463358, 2025). "Early growth response protein 1 (Egr-1)—a negative regulator of FOXC2—is highly expressed in obesity and IR models." (PMID 41404514, 2025). "Egr1 knockout mice show protection from diet‐induced obesity, fatty liver, hyperinsulinemia, and hyperlipidemia suggesting that Egr1 is a causal factor in these symptoms." (PMID 39609264, 2025). "There were no obvious alterations in whole-body weight until 21 months of age, when obvious obesity was found in liver-specific Egr-1 KO mice compared with wild-type (WT) mice." (PMID 36964140, 2023). "Experimental evidence supports that EGR-1 protein is a mediator for lipotoxicity-induced cytokine gene expression in the placentas from pregnant women with obesity, suggesting a relevant contribution to the effects of obesity on fetal programming." (PMID 36072345, 2022). "Similar to kidney ECs, neural ECs showed downregulation of AP1 transcription factor subunit genes Fos, Fosb, Jun, Junb, Jund and Egr1 in obesity." (PMID 36400935, 2022). "In contrast to cardiac artery ECs, renal ECs generally showed reduced expression of AP1 transcription factor subunit genes Jun, Junb, Jund, Fos, Fosb and Egr1 in obesity." (PMID 36400935, 2022). "Consistently, Egr1−/− mice are protected from high fat diet-induced obesity via an increase of energy expenditure." (PMID 32121305, 2020). "The NF-κB target genes IRF1, STAT1, JUN, HSP90AA1, FOS, and EGR1, were enriched in the pathway of Glucocorticoid receptor regulatory network and homeostasis pointing towards their critical role in obesity." (PMID 31013288, 2019). "Among these genes, only Egr1 and Klf5 expression and motif enrichment were enhanced by exercise, though obesity had a blunting effect." (PMID 29044196, 2017).
Obesity (continued). "In this context, Egr-1 null mice would be protected against obesity-related complications, such as elevated circulating TG levels, by a mechanism possibly mediated by FOXC2, increasing energy expenditure and altering mitochondrial function." (PMID 27478511, 2016). "Additionally, mesenchymal stem cell overexpression of EGR1 inhibits white adipose tissue browning, increases energy expenditure, and mitigates obesity-related metabolic abnormalities." (PMID 40244284, 2025). "EGR1 has been also shown to participate in IR development by causing Serine phosphorylation of IRS-1 in adipocytes and loss of EGR1 in mice protected them from obesity, IR, hyperlipedimia, and hyperinsulinemia." (PMID 35987697, 2022). "DNA microarray analysis revealed that the cardiac tissue level of early growth response protein 1 (EGR-1), which activates angiogenesis, was significantly reduced in untreated mice with dietary obesity, while this decrease was inhibited by administration of linagliptin." (PMID 28771625, 2017). "Moreover, a strong correlation between Egr1 expression levels with dietary-induced obesity has been found in both mice and humans." (PMID 27478511, 2016). "Although EGR1 and TNMD genes share the same expression profile in white adipose tissues of obese patients, in contrast to EGR1, TNMD acts as a protective factor in visceral adipose tissue to alleviate insulin resistance in obesity." (PMID 32121305, 2020). "In our results, the induction of the mRNA levels of adiponectin, FgfR1, FgfR4 and Egr1 in scWAT of HFDM mice indicates that, in obesity, maqui supplementation increases the sensitivity to FGF21 of scWAT." (PMID 31480627, 2019). "Our present results also suggested that DPP-4 inhibits FGF-2/EGR-1/VEGF-A signaling to promote cardiac capillary rarefaction and cardiac dysfunction in mice with dietary obesity." (PMID 28771625, 2017). "However, gECs showed increased expression of Fos, Fosb and Egr1 and increased expression of FGF receptor, nerve growth factor and IGF1 signaling networks in obesity." (PMID 36400935, 2022). "EGR1 directs tendon differentiation, promotes tendon repair and blocks energy expenditure via direct uncoupling protein 1 (UCP1) transcription repression and counteracts obesity." (PMID 33613572, 2020).
ovarian carcinoma (29 papers, 2009 to 2025). A malignant neoplasm originating from the surface ovarian epithelium. "MGRN1 mRNA expression was also strongly associated with EGR1 mRNA expression in the ovarian cancer population (P<0.01)." (PMID 34268111, 2021). "Ovarian cancer cell line studies have also demonstrated that low levels of EGR1 are associated with PTX resistance." (PMID 29719592, 2018). "We also report a significant downregulation of EGR1 in response to JIB-04 inhibitors in ovarian cancer cells." (PMID 40664642, 2025). "In ovarian cancer, EGR-1 mediated epidermal growth-factor-induced downregulation of E-cadherin expression via Slug in ovarian cancer cells." (PMID 36233659, 2022). "Further, EGR1 contributes to tumor invasion and metastasis in ovarian cancer cells by activating the expression of SNAIL and SLUG which are involved in MAPK signaling pathway and cause E-cadherin transcriptional loss." (PMID 35906698, 2022). "Our own previous research found that HE4-mediated suppression of EGR1 in ovarian cancer cells led to chemoresistance." (PMID 36131935, 2022). "Knockdown of EGR1 expression can decrease cisplatin-induced apoptosis in a variety of cancer cells, while overexpression of this gene sensitizes ovarian cancer cells to cisplatin-induced apoptosis." (PMID 34268111, 2021). "We also determined that inhibition of DUSP6 promotes chemosensitivity of two different ovarian cancer cell lines, which coincided with increased expression of pro-apoptotic EGR1, and reduced expression of oncogenic c-JUN." (PMID 31164954, 2019). "A previous study showed that EGF increases the invasion of ovarian cancer cells through EGR1 upregulation." (PMID 30845713, 2019). "EGR1 is a transcription factor involved in promoting apoptosis in many cancers, and is involved in cisplatin resistance in esophageal and ovarian cancer cells." (PMID 31164954, 2019). "Silencing of EGR1 has been shown to promote resistance to cisplatin in esophageal cancer cells, while overexpression of this gene sensitizes ovarian cancer cells to cisplatin-induced apoptosis." (PMID 27184254, 2016). "Similar to ovarian cancer, miR-192 treatment mediated a robust downregulation of EGR1 and HOXB9 levels and significant decreases in several angiogenic factors including IL6, IL8 and EFNA1; consistent with the pattern observed after siEGR1/siHOXB9 treatment." (PMID 27041221, 2016). "Here, we report for the first time ZHX1 promotes the proliferation, migration, and invasion of CCA cells, and that it upregulates EGR1, which has been previously shown to promote progression of various cancers including prostate and ovarian cancer." (PMID 27835650, 2016). "It is recently reported that ERK1/2 activation mediates the expression of EGR1, which subsequently increases the invasive capability of ovarian cancer cells." (PMID 24053380, 2013). "The disruption of multiple neighbor nodes to EGR1 by different regulatory mechanisms highlights the complex nature of the controls on this key suppressor gene for ovarian cancer." (PMID 22863767, 2012). "An identical role of EGR1 has been reported in prostate, liver, and ovarian cancers." (PMID 38944814, 2024). "Moreover, the down-regulation of ATG14 by EGR1-miR152 was shown to sensitize ovarian cancer cells to cisplatin-induced apoptosis by inhibiting cytoprotective autophagy." (PMID 32727463, 2020). "EGR1 is a cancer-suppressing gene known to be down-regulated in ovarian cancer." (PMID 22863767, 2012). "As a consequence, we additionally tested the expression of Egr-1 in ovarian cancer cell lines." (PMID 19904262, 2009). "We reveal that MECOM-mediated transcriptional regulation of KRAS activates KRAS/ERK/EGR1 signaling axis, contributing to MECOM’s oncogenic activity in MECOM-dependent ovarian cancers." (PMID 40664642, 2025). "Analyzing the effect on cellular proliferation, we observed downregulation of EGR1 in JIB-04-treated mice tumors, as was seen in ovarian cancer cells." (PMID 40664642, 2025).
ovarian carcinoma (continued). "MYC, EGR1, and miR-130a-3p were hubs in our integrative analysis of ovarian CSC-enriched SFCs, suggesting that ovarian cancer SFCs display a stem cell identity with the quiescent phenotype where adhesion- and cell cycle-related genes were suppressed." (PMID 32046751, 2020). "The downregulation of EGR1 and HOXB9 by miR-192 was further confirmed in another ovarian cancer cell line, HeyA8." (PMID 27041221, 2016). "Below, we provide in-depth descriptions of the heterogeneous regulatory networks that affect a key tumor suppressor gene (EGR1) and an oncogene (AKT) in ovarian cancer." (PMID 22863767, 2012). "Up-regulation of both EGR1 and miR-152 inhibit the downstream target genes of miR-152, and ATG14, thus suppressing cisplatin resistance in ovarian cancer cells by preventing protective autophagy in ovarian cancer cells." (PMID 38244586, 2024). "Notably, two MEK inhibitors (PD0325901 and Trametinib) were effective in eliminating ovarian cancer cells in combination with JQ1, consistent with our observation that JQ1 treatment activated MAPK targets EGR1 and FOS." (PMID 26575423, 2016). "Interestingly, while both EGR1 and ATF3 are well studied as stress-responsive transcription factors, ATF3 emerged as a gene of interest since it is a master transcription factor that regulates immunity and inflammation, but little is known about its role in ovarian cancer." (PMID 36131935, 2022).